CXCR4 (C-X-C motif chemokine receptor 4)
Diseases named in the same sentence as CXCR4 in open-access papers (continued):
Sharing a sentence is not in itself a finding about the gene and the disease.
oral cancer (continued). "Interestingly, CXCR-4 positive cells showed positive staining for PKC-δ and CD133 in oral cancer tissue and cell lines." (PMID 34885003, 2021). "The co-expression of CXCR-4/PKC-δ and CXCR-4/CD133 in oral cancer tissues and cell lines suggest that they may have a functional interaction in oral cancer cells." (PMID 34885003, 2021). "Thus, in this study, we examined target miRNAs regulated by the SDF-1/CXCR4 system in B88-SDF-1 cells using miRNA microarrays and investigated their functional role on metastasis in oral cancer." (PMID 25536052, 2014). "The mechanism of miR-518c-5p upregulation by the SDF-1/CXCR4 system in oral cancer cells was not clarified in the present study." (PMID 25536052, 2014). "In our previous study, we detected CXCR4 expression in approximately 60% of primary oral cancers and concluded that CXCR4-positive cases had a significantly worse prognosis than CXCR4-negative cases." (PMID 24236200, 2013). "Although recently attentions have been paid to the relationship between CXCR4 and oral cancer, until now, no report focuses on the alterations of CXCL12/CXCR4 axis in premalignant stage of oral cancer." (PMID 22496601, 2012). "Chemotherapy is a powerful tool for the treatment of oral cancer, including oral SCC; however, the effects of chemotherapeutic agents on the expression of CXCR4 are unknown." (PMID 19671192, 2009). "CXCR-4, PKC-δ and CD133 might regulate aggressiveness and invasion of oral cancer cells." (PMID 34885003, 2021). "Although vesnarinone was not developed as a targeted agent against CXCR4, it may have other targets against the metastasis of oral cancer." (PMID 19671192, 2009). "Initially, two conventional cytocidal chemotherapeutic agents for treating oral cancer, namely 5-FU and CDDP, were assessed, but the expression of CXCR4 mRNA was not altered with these treatments." (PMID 19671192, 2009).
pancreatic adenocarcinoma (25 papers, 2009 to 2025). "In a pancreatic adenocarcinoma slice culture system, the combination of CXCR4 inhibition and PD-1 blockade led to redistribution of CD8+ T cells from the stroma into the tumor, T-cell proliferation, clonal T-cell expansion, and cancer cell death." (PMID 36923305, 2022). "We recruited a pilot study of 30 blood samples from PC patients diagnosed with pancreatic adenocarcinoma to screen with the CXCR4 assay model." (PMID 35259193, 2022). "circUBAP2 modulates pancreatic adenocarcinoma tumorigenesis by regulating the levels of hsa-miR-494 and the expression of CXCR4, HIF1A, ZEB1, SDC1, and TWIST132." (PMID 33707417, 2021). "Its main receptor CXCR4 is expressed by circulating cancer stem cells of pancreas adenocarcinoma, which in turn contribute to metastasis." (PMID 30670778, 2019). "We found that CXCR4 was expressed on significant percentages of major types of kidney, lung, and pancreatic adenocarcinomas." (PMID 29088715, 2017). "Among solid tumors, we found expression of CXCR4 on significant percentages of major types of kidney, lung, and pancreatic adenocarcinomas, and, notably, on metastases of clear cell renal cell carcinoma and squamous cell carcinoma of the lung." (PMID 29088715, 2017). "The CXCL12/CXCR4 axis plays an important role in the progression and organ-specific metastasis of pancreatic adenocarcinoma." (PMID 23181100, 2012). "In addition to SSTR subtypes, several immunohistochemical studies showed the distribution of CXCR4 in pancreatic adenocarcinoma." (PMID 38203605, 2023). "CircUBAP2 (hsa_circ_0007367) was shown to repress antigen presentation and induce immune escape in pancreatic adenocarcinoma (PAAD) through sponging miR-494 to upregulate CXCR4 and ZEB1 proteins, then leading to increased expression of CTLA-4 and PD-1." (PMID 38177102, 2024). "In pancreatic adenocarcinoma (PAAD), the circ_0003945/miR-494 axis regulated PAAD progression by CXCR4 and ZEB1, key mediators of tumor immune cell infiltration." (PMID 38711855, 2024). "Studies have found that the overexpression of CXCR4 and ZEB1 genes in pancreatic adenocarcinoma (PAAD) tissues is regulated by circUBAP2." (PMID 40034598, 2025). "In pancreatic adenocarcinoma (PAAD), circ-UBAP2-hsa-miR-494 potentially targets CXCR4 and ZEB1 transcripts." (PMID 32943996, 2020). "In pancreatic adenocarcinoma (PAAD), circ-UBAP2 promotes M2 polarization of TAMs by targeting CXCR4 and ZEB1, which enhances tumor proliferation." (PMID 40296917, 2025). "Accordingly, CXCR4-overexpressing specimens from TCGA database were characterized by higher levels of infiltrating CD8+ T cells—especially in entities such as clear cell (KIRC) and papillary renal cell carcinoma (KIRP), pancreatic adenocarcinoma (PAAD), and thymoma (THYM)." (PMID 36672341, 2023). "It was identified that the expressions of CXCR4, HIF1A, ZEB1, and SDC1 in pancreatic adenocarcinoma (PAAD) were controlled by circ-UBAP2 and miR-494." (PMID 32665846, 2020).
B cell lymphoma (24 papers, 2012 to 2025). "In particular, somatic CXCR4 mutations have been reported in indolent forms of B-cell nHL, follicular lymphoma, and WM." (PMID 32784523, 2020). "Among the chemokine receptors, the C-X-C chemokine receptor type 4 (CXCR4) is notably prominent in many B-cell lymphomas." (PMID 40076664, 2025). "Molecularly targeted imaging studies have revealed enhanced CXCR4 expression in various B-cell non-Hodgkin lymphomas." (PMID 34363012, 2021). "In cooperation with the oncogene TCL1, CXCR4 hyperactivation even favors development of aggressive B-cell lymphoma." (PMID 34363012, 2021). "To further support the finding that CXCR4 hyperactivation potentiates oncogenic programs, we used the Cancer Gene Census and human B-cell lymphoma datasets for cross-species validation." (PMID 34363012, 2021). "Collectively, these observations strengthen the biological relevance of CXCR4 and the crucial impact of its genomic landscape in the pathogenesis of B-cell NHL malignancies." (PMID 32260318, 2020). "Flow cytometry analysis showed LY2624587 antibody induced receptor mediated internalization and downregulation of cell surface CXCR4 in human B cell lymphoma Raji cells." (PMID 29212254, 2017). "In the present study, we observed characteristic constellation of CXCR4 expression, which was increased in B cell lymphomas, as well as in reactive lymph nodes." (PMID 24859274, 2014). "We showed that the average expression of CXCR4 in reactive lymph nodes is similar to that of the B-cell lymphoma nodes." (PMID 24859274, 2014). "Three articles described the application of immuno-PET in CD20+ B-cell lymphomas, while the fourth article dealt with CD184 (better known as CXCR4, chemokine receptor type 4, or fusin) targeting with [68Ga]pentixafor in patients with non-Hodgkin’s lymphoma (NHL)." (PMID 35884548, 2022). "To further explore the association of MYC and CXCR4 expression, we analyzed patient datasets and found a significant correlation of MYC mRNA and IG-MYC translocation status with CXCR4 mRNA expression in B-cell lymphoma patients." (PMID 34363012, 2021). "In this study, we demonstrated that the CXCR4 antagonist EPI-X4 and its optimized derivative, JM#21, effectively enhance the therapeutic effects of CD19-targeted immunotherapy in B-cell lymphomas, particularly in DLBCL and WM." (PMID 40076664, 2025). "This was consistent with our study that Cxcr4 was highly expressed in two types of B cells (CD43−) and B cell (CD19+), two types of B cell lymphoma A20 and CH12.LX, and Spleen." (PMID 34180954, 2021). "Hyperactivated CXCR4 functioned as an oncogene cooperating with TCL1 to accelerate CLL progression and development of aggressive B-cell lymphoma." (PMID 34363012, 2021). "To functionally investigate the role of CXCR4 hyperactivation in the context of aggressive B-cell lymphoma, we chose the Eμ-Myc mouse model, which is characterized by B-cell-targeted overexpression of MYC, leading to MYC-driven aggressive B-cell lymphoma." (PMID 34363012, 2021). "MYC can bind and activate the CXCR4 promoter, but this connection has not been explored in B-cell lymphoma so far." (PMID 34363012, 2021). "Furthermore, data from large B-cell lymphoma patient datasets revealed a correlation of MYC and CXCR4 expression and an increase of CXCR4 expression in patient samples with translocation of MYC further supporting a regulation of CXCR4 by MYC in a B-cell oncogenic context." (PMID 34363012, 2021). "Likewise, high levels of CXCR4 mRNA expression were found in OSW and Zach, which are both T cell lymphomas, but no expression was seen in canine B cell lymphomas." (PMID 33166332, 2020).
Cerebral ischemia (24 papers, 2005 to 2025). Restriction of arterial blood supply to the brain associated with insufficient oxygenation to support the metabolic requirements of the tissue. "These insights into the effects of the SDF‐1α/CXCR4 axis on cerebral ischemia and plasticity reveal new evidence for the effectiveness of rTMS for the treatment of PSCI." (PMID 41355332, 2025). "CXCR4 encodes a well-known receptor for chemokine CXCL12, which is mainly produced by damaged neurons after cerebral ischemia." (PMID 34154653, 2021). "In a rat cerebral ischemia/reperfusion model, it is reported that both CXCR-4 and CXCR-7 receptors were co-expressed in bone marrow-derived MSCs and synergistically promoted their migration even though the effect of CXCR-7 was stronger than that of CXCR-4." (PMID 32000804, 2020). "The expression of CXCL12 was significantly upregulated after cerebral ischemia, leading to chemotaxis of endothelial progenitor cells expressing CXCR4." (PMID 33381162, 2020). "CXCR4/SDF-1 can also potentially promote neurogenesis to prevent local damage to the antineuronal area after brain ischemia." (PMID 31658727, 2019). "CXCR4 overexpression with lentiviral transduction in the MSCs promoted their migration and enhanced neuroprotection in a rat model of cerebral ischemia." (PMID 28499457, 2017). "Consistently, in the case of cerebral ischemia, elevation in the level of MMP-9 via glycogen synthase kinase-3β suppression caused an increase in CXCR4 expression for subsequent mediating BMMSCs migration." (PMID 27130910, 2016). "Many researches have shown that BMSCs can migrate to injured tissues via the SDF-1α/CXCR4 axis and relieve myocardial infraction, promote wound healing, heal bone fracture, reduce cerebral ischemia, and ameliorate acute necrotizing pancreatitis." (PMID 25810724, 2015). "Numerous studies have reported that BMSCs utilize the SDF-1/CXCR4 axis to migrate to damaged tissues in several pathological conditions, including myocardial ischemia, wound area, bone fracture and cerebral ischemia." (PMID 24626964, 2014). "Cxcr4 are key regulator of neuro-repair processes after brain ischemia and spinal cord injury; inhibiting Cxcr4 can enhance re-myelination and improve recovery." (PMID 23951329, 2013). "It suggested that S-MSCs may promote rats’ nerve regeneration after focal cerebral ischemia-reperfusion injury via CXCR4, which possibly is one of the mechanisms of S-MSCs protecting the brain." (PMID 35625017, 2022). "CXCR4 is essential for an innate immune system-mediated defense response after cerebral ischemia." (PMID 34539341, 2021). "Other studies have indicated that the SDF1α/CXCR4 axis plays an important role in BMSC mobilization in other inflammatory conditions, such as myocardial ischemia, brain ischemia, wound healing, or AP." (PMID 35846982, 2022). "It is noteworthy that CXCR4 is expressed in the NPCs and the actions of the SDF-1/CXCR4 complex are critical for the migration of NPCs to SDF-1-riched injury sites after cerebral ischemia." (PMID 29123467, 2017). "At present, the evidences of the role of SDF-1/CXCR4/CXCR7 in remyelination mainly focus on demyelinating disease, especially in MS models, there are few studies on cerebral ischemia and brain injury." (PMID 29123467, 2017). "Neural progenitor cells and neuroblasts express CXCR4 and are attracted by SDF-1α developmentally and following brain ischemia." (PMID 16259636, 2005). "All modalities of neurological behavior measurement of ischemic rats receiving the specific IGF1R inhibitor (PPP) or CXCR4-Ab (mAb 173) injection in U-IGF1R+ hDSC-implanted group showed almost no recovery similar to that of the vehicle control after cerebral ischemia." (PMID 27586516, 2016).
neuroendocrine tumors (24 papers, 2012 to 2026). "For that reason, this review describes the significance of CXCR4 and its possible clinical applications in the diagnostic and therapeutic management of neuroendocrine neoplasms." (PMID 38791878, 2024). "Loss of Somatostatin Receptor 2 (SSTR2) expression and rising CXC Chemokine Receptor Type 4 (CXCR4) expression are associated with dedifferentiation in neuroendocrine tumors (NET)." (PMID 33671498, 2021). "The overexpression in cell membranes of CXCR4 has been shown to be associated with the development of different kinds of histological malignancies, such as adenocarcinomas, epidermoid carcinomas, mesenchymal tumors, or neuroendocrine neoplasms (NENs)." (PMID 38791878, 2024). "And several previous studies have explored CXCR4 expression in neuroendocrine tumors, but these studies generally took GEP-NENs as a whole rather than focusing on GEP-NENs G3, and the number of specimens included in these studies was also generally small." (PMID 38524630, 2024). "This study suggested that high CXCR4 expression was more likely to lead to a diagnosis of NEC, CXCR4 can be used in the diagnosis of high-grade neuroendocrine tumors." (PMID 38524630, 2024). "Accordingly, in neuroendocrine neoplasms an inverse expression of the SSTs and CXCR4 with increasing malignancy of the tumours has been observed." (PMID 35799158, 2022). "This is also supported by a study that demonstrated an inverse correlation between tumor differentiation and CXCR4 expression, as assessed by immunohistochemistry of surgical samples in neuroendocrine neoplasms." (PMID 34885030, 2021). "When evaluating the associations between FAM159B and typical neuroendocrine tumour markers, positive associations were observed between the IRS values of FAM15B and those of the dopamine receptor D2, SST1, SST2, SST3, SST5, CXCR4 and PD-L1." (PMID 34830137, 2021). "In solid malignancies, pilot studies have hinted at a role for CXCR4-directed imaging in various selected diseases, such as small cell lung cancer, esophageal adenocarcinoma, and poorly differentiated neuroendocrine neoplasms." (PMID 31475113, 2019). "The most recent data for gastro-entero-hepatic neuroendocrine tumors showed a better but still imperfect correspondence between CXCR4 positivity of tumor biopsies and 68Ga-pentixafor positivity by PET." (PMID 29088715, 2017). "Data on CXCR4 expression in gastroenteropancreatic neuroendocrine neoplasms, however, are limited so far." (PMID 26259237, 2015). "In the present study, the co-expression of the SSTR subtypes 1, 2A, 3 and 5 with CXCR4 was analyzed in G1–G3 neuroendocrine neoplasms." (PMID 26259237, 2015). "While CXCR4 expression has only been described for a limited number of neuroendocrine neoplasms, more comprehensive data are available for SSTR." (PMID 26259237, 2015). "In addition, CXCL12 promotes EMT-like changes and osteotropism in CXCR4 high/CXCL12 low neuroendocrine tumor (NET) cells via CXCR4." (PMID 40860192, 2025). "Neuroendocrine tumors have been established to possess receptors for SDF1 (CXCR4)." (PMID 38341509, 2024). "From these studies, it appears that there may be a role for CXCR4-directed imaging in patients with higher grades (G2 and G3) of neuroendocrine tumours." (PMID 36140541, 2022). "Understanding the mechanisms regulating CXCR4 expression and function would give further insight into the molecular processes defining the more aggressive phenotype of CXCR4-expressing neuroendocrine tumors and would help to enhance CXCR4-directed imaging and therapy." (PMID 33671498, 2021). "Thus, the present investigation aimed to determine whether different SSTR (SSTR1, 2A, 3 and 5) and CXCR4 are co-expressed in G1-G3 neuroendocrine tumors and carcinomas by means of immunohistochemistry, using highly specific monoclonal antibodies." (PMID 26259237, 2015). "As neuroendocrine neoplasms (NEN) undergo increasing dedifferentiation, CXC chemokine receptor type 4 (CXCR4) becomes upregulated." (PMID 41620429, 2026).
neuroendocrine tumors (continued). "Among those, 12/42 (28.6%) had a median SUVmax above 10 (ACC, 5/12 [41.7%]; neuroendocrine neoplasms, 4/12 [33.3%]; SCLC, 2/12 [16.7%]; DSCRT, 1/12 [8.3%]), thereby possibly rendering those patients eligible for CXCR4-targeted “cold” inhibitory drugs or RLT." (PMID 38082196, 2024). "Both CXCR4/CXCL12 signaling as well as Wnt signaling have been shown to induce cell migration, expression of Epithelial–Mesenchymal Transition (EMT) markers, and proliferation in neuroendocrine tumors in vitro." (PMID 33671498, 2021).